GIPR (gastric inhibitory polypeptide receptor)
Diseases named in the same sentence as GIPR in open-access papers (continued):
Sharing a sentence is not in itself a finding about the gene and the disease.
Obesity (continued). "Thus, it is of particular interest to elucidate GIPR sites of action and mechanisms mediating its effects on obesity." (PMID 31403469, 2019). "The genetic ablation of either the GIPR or of GIP-secreting enteroendocrine cells prevented the onset of obesity and increased fat oxidation under high-fat diets through an unknown mechanism." (PMID 27112963, 2017). "To avoid overlooking the heritability of obesity traits due to unknown interactions between GIP and GIPR variants, we performed gene–gene interaction (epistasis) analyses." (PMID 28530680, 2017). "Although the mechanisms underlying the anti-obesity effects of WB remains uncertain, the extrapancreatic GIP/GIPR signaling activity may play a significant role in increasing fat oxidation." (PMID 28970776, 2017). "In obese ob/ob mice, in which a defect in the leptin gene results in hyperphagia and subsequent obesity, genetic ablation of GIPR improved not only obesity by increasing energy expenditure, but also insulin insensitivity and glucose tolerance without seriously affecting insulin secretion." (PMID 26075286, 2015). "Conversely, reduced body weight gain has been observed in diet-induced obesity models in a GIPr−/− knock-out mouse, upon immunization with GIP to generate antagonistic antibodies, and upon administration of the GIPr peptide antagonist Pro3GIP or ablation of GIP-producing K cells." (PMID 23689510, 2013). "It has been shown that GIPR is involved in obesity and insulin resistance." (PMID 24086540, 2013). "Whereas the related incretin hormone GLP-1 has found widespread therapeutic use, the complex nature of GIP biology has meant that proposals for agonism or antagonism of the GIPr for the treatment of diabetes and obesity have yet to lead to therapeutic applications." (PMID 23689510, 2013). "Subsequent studies with GIPR-/- mice revealed that GIP is an obesity promoting factor." (PMID 20673334, 2010). "The study reported that GIPR-/- mice were resistant to ovariectomy induced obesity." (PMID 20673334, 2010). "However, there has been a rekindling of interest in GIP biology in recent years, in great part due to pharmacology demonstrating that both GIPR agonism and antagonism may be beneficial in treating obesity and diabetes." (PMID 40024571, 2025). "Interestingly, a recent study has reported that retatrutide, a triple agonist of glucagon receptor (GCGR), glucose-dependent insulinotropic polypeptide receptor (GIPR) and GLP-1R, alleviated tumor growth and chemotherapy resistance in obesity-associated triple-negative breast cancer." (PMID 41244507, 2025). "However, the opposing idea that endogenous GIP is pro‐adipogenic is supported by findings that mice lacking Gipr are protected against diet‐induced obesity and that humans with loss of function GIPR variants have a lower average body mass index." (PMID 39576749, 2025). "Recent years have seen a rise in the use of glucagon-like peptide-1 (GLP-1) receptor agonists and dual GLP-1 and gastric inhibitory polypeptide receptor agonists, which may have implications for obesity management and potentially influence the prevalence of SLD." (PMID 40906892, 2025). "However, there is an ongoing debate on whether increasing or decreasing GIPR agonism can benefit body weight and metabolism, in part based on the observation that GIPR-null mice are protected against obesity." (PMID 40892365, 2025). "Furthermore, the inhibition of endogenous GIP or GIPR confers resistance to diet-induced obesity." (PMID 39940910, 2025). "Moreover, tirzepatide’s engagement with GIPR in adipose and pancreatic tissue contributes to enhanced metabolic flexibility and β-cell preservation, highlighting its advantage as a multi-target agent for obesity." (PMID 41226200, 2025).
Obesity (continued). "However, this is not supported by distinct differences in the metabolic phenotype induced by GIPR agonism vs. antagonism in various animal models of obesity-diabetes, with the latter intervention alleviating insulin resistance and inducing β-cell rest [169,272,1014,1015,1022]." (PMID 40024571, 2025). "Although the incretin effects of GIPR undoubtedly play a crucial role in preventing postprandial glucose excursion, there is still intensive debate on whether the GIPR should be activated or inhibited for the treatment of obesity." (PMID 39114288, 2024). "Thus, with continuing development on GIP/GLP-1R co-agonists modalities, it is hoped that clarity can be ascertained as to whether GIPR agonism or antagonism has the greatest role to play in management of obesity and related metabolic diseases." (PMID 38861364, 2024). "Hence, the extrapancreatic actions of GIPR signaling extend to the attenuation of gut inflammation, findings with potential translational relevance for clinical strategies modulating GIPR action in people with type 2 diabetes or obesity." (PMID 39723966, 2024). "Notably, however, our findings suggest that future obesity therapies designed to modulate GIPR signaling, whether by agonism or antagonism, would be best targeted towards GABAergic neurons." (PMID 39612941, 2024). "However, debate has long surrounded the use of the GIPR as a therapeutic target and whether agonism or antagonism is of most benefit in management of obesity/diabetes." (PMID 38861364, 2024). "While these features are associated with a LoF phenotype, other studies suggest that both GIPR agonists and antagonists may provide benefits to T2D and obesity, indicating a complex mechanism of GIPR action within the processes of blood glucose and weight regulation." (PMID 37091864, 2023). "According to the report by Finan, the GLP-1R/GIPR dual-agonists could provide more significant hypoglycemic, hyperlipidemic, and anti-obesity effects compared with single agonists with attenuated gastrointestinal discomfort and nausea (typically associated with GLP-1R agonists)." (PMID 37514148, 2023). "However, there is ambiguity on whether activation or inhibition of GIPR has beneficial effects on obesity." (PMID 37443835, 2023). "Meanwhile, research on the mechanism and efficacy of GLP-1R/GIPR dual agonists and GLP-1R/GIPR/GCGR triple agonists paves the way to a ground-breaking therapy specific for obesity, which suggests multi-target drugs may have more advantages than a single target." (PMID 36843578, 2023). "Thus “triple agonism” of GLP-1R, GIPR, and GcgR could represent a new standard for pharmaceutical intervention in obesity." (PMID 35809773, 2022). "In light of this imperative crosstalk between metabolism and type 2 immune cells within fat depots, we examined here whether deletion of GIPR signaling in immune cells, and the resulted impairment in energy homeostasis during obesity, is due to the alteration of fat depot type 2 immunity." (PMID 33717200, 2021). "Interestingly, these genes, with the exception of MC4R, KSR2 and GIPR, have not previously been implicated in obesity, suggesting that key biologic mechanisms underlying obesity have yet to be identified." (PMID 32955435, 2020). "In addition, daily injection of a specific GIPR antagonist protects mice against obesity." (PMID 28970776, 2017). "In view of the glucose intolerance but resistance to diet-induced obesity observed in GIPR knockout mice, the current study was initiated to test the hypothesis that chronically elevating GIP levels in vivo would increase adipose tissue expansion and exert beneficial effects on glucose homeostasis." (PMID 22802954, 2012). "This led to the suggestion that GIPR antagonist may be useful in treating type 2 diabetes in European population where it is closely related to obesity and GIPR agonists may give a good indication with diabetes related to impaired insulin release, especially in Asia." (PMID 20673334, 2010).
Obesity (continued). "In conclusion, this study characterises the metabolic effects of GIPR agonist and antagonist administration in both lean and HFD‐induced mice, providing novel insights highly relevant to the personalisation of obesity treatments." (PMID 41287212, 2026). "While numerous proof-of-concept candidate molecules have been disclosed, the only approved example of multi-receptor agonism for obesity and T2D is the dual GLP-1R/GIPR co-agonist tirzepatide (marketed as Mounjaro® and Zepbound®)." (PMID 39963285, 2025). "Recent years have seen remarkable advancements in obesity treatment achieved by the development of new drugs that combine GLP-1R and GIPR co-agonism in a single molecule." (PMID 40892365, 2025). "In contrast to GLP-1, which is used with success for the treatment of type 2 diabetes (T2DM) and obesity, GIP receptor (GIPR)–based agonism alone produces limited biological and pharmacological effects." (PMID 40532005, 2025). "These preclinical findings support clinical trial results showing that tirzepatide, a dual GIPR/GLP-1R agonist, exhibits greater anti-obesity effects than GLP-1 receptor agonists alone." (PMID 40607142, 2025). "Dual agonists targeting glucagon-like peptide-1 receptor (GLP1R) and glucose-dependent insulinotropic polypeptide receptor (GIPR) are breakthrough treatments for patients with type 2 diabetes and obesity." (PMID 40830598, 2025). "For example, genetic variants in GLP-1R (glucagon-like peptide-1 receptor) and GIPR (glucose-dependent insulinotropic polypeptide receptor) may modulate the effectiveness of incretin-based therapies, while PRS for satiation can help match individuals to the most appropriate anti-obesity medications." (PMID 41009961, 2025). "We also highlight the power of our approach by interrogating the internalization behaviour of GIPR and GLP1R, two main targets in the treatment of diabetes and obesity." (PMID 39610654, 2025). "The most recently approved FDA medication for the treatment of obesity, tirzepatide, exerts its physiologic effects as a dual GLP-1R and Gastric Inhibitory Polypeptide Receptor (GIP-R) agonist with better efficacy than the standalone GIP-R agonist semaglutide." (PMID 40722684, 2025). "The development of treatment strategies that target both the GIPR and the GLP-1R system represents a significant breakthrough in the fight against obesity and T2DM." (PMID 40532005, 2025). "The development of the GLP1R/GIPR dual agonist tirzepatide brought new insights into the role of GIP in the treatment of T2D and obesity because it can reduce both plasma glucose and glycated haemoglobin more effectively than the GLP1R agonist semaglutide." (PMID 39576749, 2025). "For example, activation of glucagon family receptors (GLP1R, GIPR, GCGR) shows therapeutic efficacy in treating type-2 diabetes and obesity; however, these receptors are expressed in multiple tissues." (PMID 41264544, 2025). "A second GLP1R/GIPR coagonist, tirzepatide (previously called LY3298176, marketed as Mounjaro® for T2D and Zepbound® for obesity, Eli Lilly) is a 39-amino acid peptide acylated at the lysine 20 residue with a C20 fatty diacid." (PMID 40166681, 2025). "The resounding therapeutic success of the GIPR/GLP-1R co-agonist, tirzepatide, has seen a resurgence of interest in GIPR modulation for the management of T2DM and obesity (Nauck & Müller 2023)." (PMID 38861364, 2024). "The dual activation of glucagon-like peptide-1 receptor (GLP-1R) and glucose-dependent insulinotropic polypeptide receptor (GIPR) has emerged as a promising therapeutic strategy for managing type 2 diabetes and obesity." (PMID 39030216, 2024). "GLP-1R agonists (GLP-1RA) are utilized clinically for the treatment of type 2 diabetes (T2D) and obesity and a single GIP receptor–GLP-1 receptor (GIPR–GLP-1R) coagonist, tirzepatide (TZP), is approved for the treatment of T2D and obesity." (PMID 39723966, 2024).
Obesity (continued). "Recently, several trials have included multi-targeting agonists of GLP-1R, GIPR, or glucagon receptor (GCGR) for the treatment of both T2D and obesity." (PMID 38850440, 2024). "It is now known that the imbalance of tirzepatide for GIPR >> GLP1R, as well as the mid-position of the fatty diacid moiety, probably lend the molecule to superior effects on glycemia (and obesity, which is covered elsewhere)." (PMID 38360354, 2024). "Recently, several multi-targeting agonists of GIPR, GLP-1R, or GCGR for treating T2DM and obesity have been in clinical trials." (PMID 36843578, 2023). "The maturation of incretin biology has led to the development of anti-obesity drugs that potently activate GLP-1R and/or GIP receptors (GIPR), setting new and even higher standards for performance." (PMID 36834794, 2023). "Some of the most recent drug developments for T2DM and obesity are the triagonists for GLP-1R, GIPR, and GCGR (GLP-1R/GIPR/GCGR)." (PMID 36145148, 2022). "Several multi-targeting agonists at GIPR, GLP-1R or GCGR, developed to maximize metabolic benefits with reduced side-effects, are in clinical trials to treat type 2 diabetes and obesity." (PMID 35217653, 2022). "Recent literature revealed that activation of GIPR in the CNS significantly decreased body weight and blood glucose in mice fed with a high-fat diet (HFD) or mice with diet-induced obesity (DIO)." (PMID 35712239, 2022). "Despite the importance of these drug classes for the treatment of diabetes and obesity, still very little is known about the localization of GLP1R and GIPR themselves." (PMID 34911028, 2021). "These and other data have spurred the development of GIPR antagonists for the treatment of T2DM and obesity." (PMID 33571454, 2021). "A connection between obesity and GIP has been reported: Plasma GIP levels in obese humans are increased, and GIPR knockout mice are resistant to high-fat diet (HFD)-induced obesity." (PMID 31509948, 2019). "On the other hand, many studies indicate that not only inhibition of GIPR, but also control of GIP secretion is effective for preventing obesity." (PMID 28970776, 2017). "However, neither mice administered long acting analogs of GIP1–42 nor GIP-overexpressing transgenic mice exhibit increases in body weight, food intake, adiposity or insulin resistance, questioning whether GIPR agonists would promote obesity in patients with type 2 diabetes." (PMID 20231880, 2010). "Therefore, GIPR agonists may benefit patients with type 2 diabetes without risk of promoting obesity." (PMID 20231880, 2010). "Tirzepatide is a dual incretin receptor agonist that interacts with both the glucose-dependent insulinotropic polypeptide receptor (GIPR) and the glucagon-like peptide-1 receptor (GLP-1R), contributing to its therapeutic effects in type 2 diabetes (T2D) and obesity." (PMID 41226200, 2025). "Previous studies in obese adults and normal mice have shown that consumption of high fat diet could affects GIPR and SREBF1 genes expression signalling that prevent obesity and improve insulin sensitivity." (PMID 40347281, 2025). "The therapeutic potential of GIPR:GLP-1R co-agonism extends beyond managing T2D and obesity." (PMID 40024571, 2025). "Whilst GIP's eponymous role in regulating insulin release is clear, the effect on energy balance of GIP remains unclear: both GIPR knockout and GIP-overexpressing mouse models are protected from high-fat diet induced obesity." (PMID 39788289, 2025). "Increased levels of GIPR expression in the ARC may contribute to increased GIP action in the ARC and may be considered a mechanism to reduce food intake through the GIP in obesity." (PMID 39940910, 2025). "Given our current finding that GIPR blockade attenuates glucose-induced AgRP neuron inhibition, we set out to test the hypothesis that HSD-induced obesity would blunt the response of AgRP neurons to DA-GIP." (PMID 40857106, 2025).
Obesity (continued). "We hence establish a crucial role of GIPR signalling in peripheral neurons in the regulation of glucose homeostasis, but not body weight, under conditions of diet-induced obesity." (PMID 40301583, 2025). "GIP or GIPR inhibition protects mice from diet-induced obesity, and administration of long-lasting GIP derivatives or transgenic overexpression of GIP has an anti-obesity effect." (PMID 39940910, 2025). "While data from these trials demonstrate improved efficacy in obesity and T2D through the addition of GCGR agonism to GLP-1R/GIPR agonism, whether these synergistic improvements are evident in kidney-related outcomes remains to be determined." (PMID 38477666, 2024). "It has been suggested that inhibiting GIPR activity and endogenous GIP may be effective in treating obesity, particularly when it is diet-induced through a high-fat diet." (PMID 39408213, 2024). "More recently, acute administration of a long acting GIPR agonist, GIPFA-085, acted via the ARC POMC neurons to suppress feeding and increase lipid utilization, while subchronic administration was shown to reduce body weight in diet-induced obesity mice." (PMID 37443835, 2023). "Agonism at the receptor for the glucose-dependent insulinotropic polypeptide (GIPR) is a key component of the novel unimolecular GIPR:GLP-1R co-agonists, which are among the most promising drugs in clinical development for the treatment of obesity and type 2 diabetes." (PMID 37592302, 2023). "Indeed, similarly to long-acting GIPR agonist (LAGIPRA), tirzepatide favoured similar protection from obesity and insulin resistance, together with increased catabolism of glucose, lipids, and branched-chain amino acids (BCAA) in BAT." (PMID 37378828, 2023). "Ultimately, elucidating the in vivo effects of GIPR agonism versus antagonism may offer insight into how each affects T2DM, obesity, and other metabolic diseases." (PMID 36719381, 2023). "As a result, antagonizing rather than activating the GIPR has been suggested as a potential therapeutic intervention for diabetes and obesity." (PMID 36774542, 2023). "Although the insulinotropic activity of GIP has now been confirmed in human studies involving a GIP receptor (GIPR) antagonist, whether GIP contributes to the development of obesity remains controversial." (PMID 34713962, 2022). "Mice lacking the GIPR are protected from diet‐induced obesity, and crossing of GIPR‐null mice with obese ob/ob mice reduces adiposity." (PMID 34713962, 2022). "Research showed that mice lacking GIPR are prevented from developing obesity induced by a high-fat diet (HFD)." (PMID 33503878, 2021). "They treated GIPR knockout mice protected against diet induced obesity (DIO) with muGIPR-Ab or non-neutralizing GIPR antibody (CTL-Ab) for 45 days, resulting in a greater reduction in body weight of the muGIPR-Ab group, compared to control group." (PMID 35054422, 2021). "While the glycemic effects of GIP receptor (GIPR) agonism are solidly confirmed, uncertainty exists as to whether GIPR should be stimulated or inhibited for the treatment of type 2 diabetes mellitus (T2DM) and obesity." (PMID 33571454, 2021). "In conclusion, we identified GIPR signaling as an important regulator of type 2 immunity networks in epiWAT and energy expenditure in ingWAT and a gatekeeper of the unrestrained activity of S100A8/A9 in myeloid cells during obesity." (PMID 33717200, 2021). "They interact with their cognate receptors (GIPR and GLP-1R), which are both members of the class B G protein-coupled receptors (GPCRs), and already recognized as targets for treatment of metabolic diseases, such as type 2 diabetes mellitus (T2DM) and obesity." (PMID 30863364, 2019). "Targeting GIPR to treat T2DM and obesity has a somewhat contradictory history." (PMID 31330984, 2019). "Additionally, numerous identified mQTL-SNPs cover previously identified GWAS loci for obesity, lipid and diabetes related traits e.g. POMC, GIPR, GRB10, FADS2, SORT1 and APOA5." (PMID 27322064, 2016).